IL10 (interleukin 10)
Diseases named in the same sentence as IL10 in open-access papers (continued):
Sharing a sentence is not in itself a finding about the gene and the disease.
infection (continued). "DM has also induced the release of interleukin-10 (IL-10), which is responsible for reducing inflammatory reactions, helping the elimination of pathogens and reducing the infection damage." (PMID 34067986, 2021). "Nlrp3−/− mice also had significantly higher anti-inflammatory cytokine IL-10 in the lungs, especially on day 3 post-infection." (PMID 34690967, 2021). "Defensin 1 also inhibited the bacteria-induced secretion of key cytokines IL-1β, IL-10, IL-12p70 and IL-23 at both post-infection time points and both MOI values, as determined by multiplex ELISA." (PMID 33843461, 2021). "One of the major cell types identified to produce IL-10 during LCMV Cl 13 infection is virus-specific Th1 CD4+ T cells." (PMID 34696381, 2021). "In fact, using a GFP-reporter mouse during K. pneumoniae lung infection, neutrophils were identified as IL-10-producing cells in lungs during the first 48 h post-infection." (PMID 33995357, 2021). "The splenic expression of macrophage deactivator Th2 cytokine IL-10 increased over the first 4 weeks of infection, indicating the role of IL-10 in disease progression." (PMID 33680991, 2021). "Human peripheral monocytes from L. braziliensis-infected patients with CL exhibited higher expression of TLR2, TLR4, TNF-α and IL-10 upon infection in vitro with L. braziliensis." (PMID 33924130, 2021). "In late seromas generated by infection or implant rupture, high levels of IL-10, IL-13 and Eotaxin and an elevated IL10/IL-6 ratio are features of the effusion milieu." (PMID 34503066, 2021). "Our study found that IL-10 levels in the experimental groups were higher than in the control group on day 21 after infection." (PMID 33717108, 2021). "Relative quantitative RT-qPCR was used to assess relative gene expression of pro-inflammatory cytokines (IL-6, IL-8, and IL-10) in the ileum of birds following E. coli challenge on 2 days after infection." (PMID 34903932, 2021). "Spleens from mice after two weeks of infection were collected and tested for the actual presence of IL-10-producing B cells." (PMID 35071041, 2021). "Higher IL-10 concentrations were seen in the treated group (HSP+PAM) compared to PAM after 6 weeks of infection." (PMID 34248935, 2021). "In LRTIs, the levels of IL-10 peak in the first days of the infection and rapidly decline becoming undetectable during convalescence." (PMID 34578465, 2021). "Here we show that neutrophils are the main myeloid cells that produce IL-10 in the lungs during the first 48 h of infection." (PMID 33995357, 2021). "iNos mRNA levels were highest 14 h after infection and decreased thereafter, whereas Tnf, Il-6 and Il-10 decreased continuously over time." (PMID 34359992, 2021). "At 6, 24, 48, and 72 h post infection, blood samples were collected, and the serum levels of 10 cytokines (GM-CSF, IL-1β, IL-6, IL-10, TGF-β1, IFNγ, IL-4, IL-8, IL-12p40, and TNF-α) were assessed." (PMID 33665221, 2021). "Remarkably, in the present study, 48 h post infection, IL-10 levels significantly increased in the toxigenic-strain-infected piglets but not in the non-toxigenic-strain-infected piglets." (PMID 33665221, 2021). "Our findings indicate that neutrophils are the most abundant cells that produced IL-10 either at 24 or 48 h post-infection." (PMID 33995357, 2021). "On the other hand, IL-10 levels were increased by 7 dpi after infection by H1N1 in the three groups, and the levels were much higher in the mice infected by H1N1 on 7 dpi of SARS-CoV-2 infection than ones in the other two groups." (PMID 34060982, 2021). "Donor NK cells were injected directly into the lungs of IL-10-deficient recipient mice infected with S. pneumoniae at 24 h post-infection, and bacterial burdens, IL-10, and lung myeloid cell populations were analyzed at 96 h post-infection." (PMID 35053151, 2021). "The expression of the two Th2-type cytokines IL-10 and IL-4 in mice was downregulated during the first 10 days post-infection." (PMID 34689797, 2021).
infection (continued). "The results showed that during the early period of infection, the expression levels of the two Th2-type cytokines IL-10 and IL-4 were higher in M. fortis than in the BALB/c mice." (PMID 34689797, 2021). "Blockade of the type I IFN receptor (IFNAR) leads to decreased PD-L1 expression on LCMV-infected DCs and on macrophages as well as a decrease in IL-10 levels in the serum early during infection." (PMID 34696381, 2021). "First, DC isolated from SND1-/- mice exhibited significantly lower CD40/CD80/CD86 expression and IL-12 production, but higher IL-10 production than wild-type mice during Cm infection." (PMID 33635920, 2021). "IL‐10 is proposed to be a master regulator of the immune system and during infection, IL‐10 inhibits Th1 cells, NK cells, and macrophage activity." (PMID 33463911, 2021). "A previous study showed that liver damage during P. berghei NK65 induced infection was mediated by IL-27 in an IL-10 independent manner." (PMID 34906158, 2021). "The IL-10/TNF-α ratio in our study at 12 hpb with infection was 6.6 ± 2.4 and rose to 11.1 ± 3.7 at the onset of symptoms." (PMID 34152806, 2021). "While it attenuates exaggerated immune responses that can lead to deleterious tissue lesions, high levels of IL-10 in the early course of an infection impair the host’s ability to mount an effective immune response." (PMID 34589087, 2021). "IL-10 is also an important anti-inflammatory cytokine that contributes to T cell tolerance, and its production was increased 200-fold 5 h post-infection upon L. monocytogenes infection." (PMID 34367171, 2021). "Surprisingly, protein levels of IL-10 at 24 h post-infection were significantly higher in C57BL/6 than BALB/c macrophages." (PMID 33617537, 2021). "In contrast, baseline (uninfected) levels of IL-10 were below the limit of detection in all three cell lines and induced upon infection." (PMID 34745115, 2021). "In this PKO murine model of persistent infection, they found that NK cells and CD4+ T cells produced high levels of IL-10 GFP for a longer time (until day 8 post-infection)." (PMID 35053151, 2021). "S. aureus in low-infection colony numbers triggers the secretion of the anti-inflammatory cytokine IL-10, yet when present in higher colony numbers, it reduces IL-10, leading to a more proinflammatory response." (PMID 34441029, 2021). "Serum levels of IL-17a at day 2 post-infection and IL-6, and IL-10 at day 3 post-infection are increased in TLR3+/- compared to CB4-infected wt mice." (PMID 34804036, 2021). "BMDMs treated with itaconate displayed increased secretion of TNF-α and a significant reduction in IL-10 secretion compared to untreated BMDMs in response to infection." (PMID 34350128, 2021). "There were significant decreases in the levels of secreted IL-1β and IL-10 in the fpt mutant-infected BALF samples versus LVS; both fpt mutant strains induced significantly less IL-1β and IL-10 secretion in the lungs at day 6 post-infection versus LVS." (PMID 34202420, 2021). "Positing interaction via il-10 and butyrate, H. diminuta-infection evoked increased il-10rα immunoreactivity in the colon was absent in antibiotic co-treated mice, and infected GF-mice displayed increased colonic il-10, but not il-10rα, mRNA." (PMID 34517928, 2021). "Decreased IFN-γ (Th1 cytokines) and increased IL-4, IL-5, and IL-10 (Th2 cytokines) during infection with S. mansoni suggested an imbalance in lymphocyte function." (PMID 34161342, 2021). "To validate the proposed interactions, we applied an in vivo approach utilising a well-established secondary abiotic IL-10−/− mouse model for infection with C. jejuni 81-176." (PMID 34183045, 2021). "We found that IL-1β (p < 0.0001), IL-6 (p < 0.001), and IL-2R (p < 0.0001) raised among patient specimens infected with A. fumigatus; IL-10 was slightly increased after infection (p < 0.05)." (PMID 34222495, 2021).
infection (continued). "As expected, GL or GM pretreatments effectively (P < 0.05) decreased the increased pro-inflammatory cytokines (IFN-γ, TNF-α, and IL-6) induced by ST infection, whereas, they increased anti-inflammatory cytokine IL-10 secretion (P < 0.05)." (PMID 34239908, 2021). "In KETRI 3928 infection however, the type 1 response is resolved, dampened by type 2 anti-inflammatory response (involving for example IL-10), resulting into chronic anaemia." (PMID 34284027, 2021). "The enhanced whole‐blood IL‐10 secretion was detected after schistosome infection, including infection with S. japonicum." (PMID 33959966, 2021). "Since infection distributed evenly in the brain, microglia isolated from different brain regions of the same animal were mixed and stimulated by M-CSF and IL-10." (PMID 34283885, 2021). "IL-10 is expressed by almost all subsets of leukocytes and protects the host from tissue damage resulting from excessive proinflammatory responses during infection." (PMID 34960620, 2021). "It has been reported that the infection with SARS-CoV-2 can cause a cytokine storm in patients with symptoms severe or critical, consisting of an increase of IL-1β, IL-4, IL-6, IL-10, IL-17, TNF-α, G-CSF, GM-CSF, IFN-γ, CCL2, CXCL8, and CXCL10." (PMID 33917837, 2021). "Over the past decade, surprising evidence has emerged suggesting an important role of MC produced IL-10 in the regulation of inflammation during infection and tissue damage." (PMID 33680987, 2021). "Infection with M. tuberculosis (Mtb) H37Rv after the onset of dysglycemia was associated with significantly increased lung pathology, lower concentrations of TNF-α, IFN-γ, IFN-β and IL-10 and a trend towards higher bacterial burden at 3 weeks post infection." (PMID 34295838, 2021). "IL-10 deficiency has furthermore been shown to play an important role for an IL-10-dependent feedback-control and host protection during infection." (PMID 34249012, 2021). "The expression of il-1b, il-6, il-8, and il-10 was increased along with the infection time, where the expression of the four genes was higher at 33°C than at 18°C." (PMID 34566956, 2021). "Overall, these data show that an alternative driver of NK cell IL-10 is sufficient to increase peripheral burdens upon oral infection with Lm." (PMID 33878120, 2021). "Levels of IFN-γ, TNF-α, and IL-1β were significantly reduced after 7 days of infection in the cultures treated with decitabine, but the quantification of IL-10 remained unchanged, suggesting an increase in anti-inflammatory ratio and control of inflammation." (PMID 33921194, 2021). "Level of IL-10, an anti-inflammatory cytokine, was found to be downregulated upon Gefitinib or Acriflavin treatment as compared to S. Typhimurium-infection." (PMID 33868285, 2021). "In their normal regulatory capacity, NKs secrete IL-10, which has been observed to play a role in immunosuppression during systemic infection but less so local infection." (PMID 34489972, 2021). "IL1β has both pro and anti-inflammatory behavior, the increase in fold change of IL1β is in synchrony with IL10 and TGFβ which shows its predominant anti-inflammatory action in establishing infection during early stage." (PMID 35011356, 2021). "Further, the immunoreactive proteins induce a strong immune response upon infection and elicit the significant production of IL-10, IFN-γ, Th1, and Th2 mediated mRNA expression and were therefore effective in vaccine production for edwardsiellosis." (PMID 34868012, 2021). "CD8 T cells are the major source of IL-10 production in the airways following infection of murine models with influenza A virus (SV5) and respiratory syncytial virus." (PMID 34393976, 2021). "Mtb-AG infection significantly upregulated the expression of inflammatory molecules S100A8, S100A9, CRP, IL23, activated NK cell marker (KLRG), and Th-2 type marker, IL10 at 1 week post infection." (PMID 34732811, 2021).
infection (continued). "IL-10 has been shown to be a critical inhibitor of neutrophil recruitment to the site of infection, seen in both IL-10 under-expression and IL-10 over-expression models." (PMID 33795743, 2021). "Another interesting result was the significant increase in the anti-inflammatory IL-10 gene transcripts in both the tissues of NVC control fish post-scuticociliate infection compared to the unaltered transcript level in the immersion group." (PMID 34925332, 2021). "Especially in the late phase of pathogen infection, IL10 serves the role in controlling the development of inflammatory diseases." (PMID 34827211, 2021). "Although higher levels of IL-10 were seen at 10 weeks after infection in the Lb group, at this point exacerbated inflammation and high numbers of parasites worsened lesions caused by L. braziliensis infection." (PMID 34248935, 2021). "Although the exact mechanisms of early INF-y vs. IL-10 expression in relation to infection outcome is uncertain, the importance of both cytokines in the delicate balance in MAP-host interactions is clear." (PMID 34485444, 2021). "Expression of the anti-inflammatory cytokine IL-10 was also increased during infections with chronic isolates." (PMID 33664232, 2021). "We showed that T. marneffei infection significantly upregulated the level of IL-10 at both mRNA and protein levels at 12 h, 24 h, and 48 h post-infection." (PMID 34339354, 2021). "It is well established that interleukin 12 (IL-12) is critical to counteracting intracellular pathogen infections, while IL-10 favors the bacteria’s intracellular survival." (PMID 34356768, 2021). "Interleukin-10 signaling was needed for parasite persistence and latency, whereas IL-10 knockout mouse models are resistant to infection." (PMID 33799892, 2021). "Unexpectedly, our results show that IL-10 functions only within the first 72–96 hours of Plasmodium blood-stage infection to promote initial helper T cell and B cell interactions, as well as B cell differentiation and survival." (PMID 33529242, 2021). "In the present study, we compared the expression levels of the Th1-type cytokines IL-1β, TNF-α and IL-6 and the Th2-type cytokines IL-4 and IL-10 in susceptible host BALB/c mice and resistant host M. fortis on different days post-infection with S. japonicum." (PMID 34689797, 2021). "Four well-described SNPs that have previously been associated with the outcomes of a CT infection are: TLR2 +2477 G > A (rs5743708), NOD1 + 32656 T −> GG (rs6958571), CXCR5 + 10950 T > C (rs3922), and IL10 − 1082 A > G (rs1800896)." (PMID 33430411, 2021). "Patients also have elevated levels of cytokines and chemokines like interleukin-6 (IL-6), interleukin-8 (IL-8), and interleukin-10 (IL-10) after infection." (PMID 34946799, 2021). "It is noteworthy that our model predicts a single peak in the expression of the anti-inflammatory cytokine IL-10 when the host is infected at CT0 versus two peaks when the infection occurs at CT12." (PMID 33788832, 2021). "Their research, as well as ours, have revealed the benefits of cytokines IL-6, IL-8, and IL-10 in accurately predicting infections with a short detection time and high sensitivity." (PMID 34925324, 2021). "The level of IL-10 at any time didn’t change compared with that of Dlm before administration (P>0.05), but was lower than that of the infection group at 4~48 h and was lower than that of the H37Rv group at 24 h (P<0.05)." (PMID 35003120, 2021). "Our study shows that after PCV13 vaccination, a chemokine that drives the recruitment of neutrophils to sites of infection was increased, with the exception of IL-10 and IL-8." (PMID 34959964, 2021). "The following sections describe the published evidence regarding the immunoregulatory role of IL-10-producing NK cells in systemic models of infection and human disease as a protective or deleterious factor in the host immune response." (PMID 35053151, 2021).
infection (continued). "infection, IL-10 increases expression in the early post-infection days in resistant rats, while pro-inflammatory cytokine levels decrease." (PMID 34070451, 2021). "IL-2-secreting CD4 T cells were only observable at later time points of infection, and very low frequencies of IL-10-secreting CD4 T cells were detected in this organ." (PMID 34959486, 2021). "Serum proinflammatory cytokines (interleukin-6 [IL-6], IL-1β, gamma interferon, and tumor necrosis factor alpha) and the anti-inflammatory cytokine IL-10 were first detected at 12 h postburn with infection and continued to increase until death." (PMID 34152806, 2021). "The expression levels of TNF-α, IL-6, IL-8, and IL-10 at different infection time points were higher than those in the control group, especially at 36 hpi." (PMID 33597007, 2021). "In the case of L. amazonensis, BALB/c mice fail to resolve the infection due to the difficulty in generating Th1 responses in addition to the parasite-specific production of IL-10." (PMID 33673117, 2021). "There are correlations reported in human HCT patients, where elevated AM GM-CSF production and elevated IL-10 have been identified in post-HCT BAL fluid and have been associated with post-HCT lung disease including both suspected and confirmed infections." (PMID 33575235, 2021). "Substantial upregulation of IL-10 combined with enriched B-cell subpopulations (Pro B and Pre B) at this phase of infection is again suggestive of Mm’s attempt to stem the inflammation and fight the infection." (PMID 34593836, 2021). "This inhibitory action is later counteracted by the accumulation of circulating IL-6 and TNF-α which upregulate IL-10 production, hence explaining the rise of a second peak in IL-10 when the infection occurs at CT12." (PMID 33788832, 2021). "We then characterized them in terms of morphology and their ability to produce IL-10, providing new insights on the functional heterogeneity of neutrophils and their roles during infection." (PMID 33995357, 2021). "To do this, we quantified bacterial loads after inducing IL-10 overexpression from day 30 to day 60 or 90 after infection." (PMID 34554927, 2021). "Five genes have been associated with both fibrosis and intensity of infection (RNASE3, IL4, IL10, IFNGI, and IL13)." (PMID 33659002, 2021). "When quantifying the cytokine profiles in BALs from mock control and RSV-infected animals, the most noticeable induction upon infection were IL-10 (day 6 p.i.), IL-8 and CXCL10/IP-10 (days 3 and 6 p.i.)." (PMID 33909707, 2021). "As such, these models’ effects of IL-10 during the early stages of infection will affect bacterial burdens during chronic infection." (PMID 34554927, 2021). "NK cells with high levels of IL-10 mRNA were also detected in the spleen and liver of infected mice by day 7 post-infection, indicating an early IL-10 production during L. donovani infection." (PMID 35053151, 2021). "B-1a cells either spontaneously or following infection produce the anti-inflammatory cytokine IL-10 in bulk amounts." (PMID 33708213, 2021). "For example, the mycelium of C. albicans binds to tool-like receptor 2 (TLR2) on monocytes, thereby increasing the level of the anti-inflammatory cytokine IL-10 during infection." (PMID 33680221, 2021). "Blood and liver NK cells are also the main source of IL-10 in acute toxoplasmosis: IL-10 production is induced by systemic IL-12 during infection dissemination." (PMID 33903735, 2021). "We have previously shown that FOXO3 activation, through inhibition of Akt signaling, at the primary site of infection dampens IL-10 release, increases antigenic presentation of APCs and results in intracellular clearance of BCG." (PMID 34122406, 2021). "Yang and his co-workers revealed that C57BL/6 mice with lower levels of IL-10 had faster clearance of the organism from the lungs after infection with MoPn than BALB/c mice." (PMID 34093528, 2021).